CD24 (CD24 molecule)
Diseases named in the same sentence as CD24 in open-access papers (continued):
Sharing a sentence is not in itself a finding about the gene and the disease.
myelofibrosis (1 paper, 2025). A partial or complete replacement of the bone marrow stroma by fibrous tissue. "In summary, this study reveals defective neutrophil clearance as a cause of pathogenic cell-cell interactions that may increase thrombocytosis and myelofibrosis risk, and postulate CD24 as a candidate innate immune checkpoint in MPN." (PMID 40373279, 2025). "Consequently, CD24 blockade improves thrombocytosis and prevents myelofibrosis in MPN mice." (PMID 40373279, 2025). "These abnormal interactions promote thrombocytosis and myelofibrosis in MPN, and can be prevented by blocking CD24." (PMID 40373279, 2025). "However, CD24 blockade in human MPN neutrophils and chronic CD24 blockade or genetic deletion in MPN mice halved active TGF-β, preventing myelofibrosis development in these mice." (PMID 40373279, 2025). "High CD24 (not CD47) protein expression was detected in BM neutrophils from mouse models of PV, ET or secondary (post-ET) myelofibrosis." (PMID 40373279, 2025).
Nephropathy (1 paper, 2021). A nonspecific term referring to disease or damage of the kidneys. "Injection of CD133+CD24+PDX− cells, but not CD133−CD24−PDX+ or CD133+CD24+PDX+ cells, into mice with Adriamycin-induced nephropathy reduced proteinuria and improved chronic glomerular damage." (PMID 34674704, 2021).
non-alcoholic fatty liver disease (1 paper, 2024). "Elevated CD24 gene expression is seen in those with non-alcoholic fatty liver disease (NAFLD), and this is thought to be a risk factor." (PMID 38279998, 2024).
oropharyngeal cancers (1 paper, 2019). Carcinoma, predominantly squamous cell, arising from the epithelial cells of the oropharynx. "In TMA, CD24 only showed a correlation to tumor stage in the subgroup of oral cavity and the selectin ligand sLeX in the subgroup of oropharyngeal cancer, respectively." (PMID 31661833, 2019).
ovarian serous tumor (1 paper, 2013). A benign, borderline, or malignant epithelial tumor of the ovary characterized by the presence of neoplastic epithelial cells that, in well differentiated tumors, resemble the epithelial cells of the fallopian tube and, in poorly differentiated tumors, show anaplastic features. "A study demonstrated that CD24 could localize in the cytoplasm of ovarian serous tumors, while normal epithelium and serous cystadenomas expressed CD24 marker in the apical membrane." (PMID 23509802, 2013).
papillary thyroid carcinoma (1 paper, 2023). "In another study, CD24 was low in papillary thyroid cancer, and its expression was negatively correlated with multifocality." (PMID 37907864, 2023).
Pca (1 paper, 2006). "Only two of 13 Pca patients with a relative CD24 expression of over 0.3 are currently in disease progression (as indicated by a PSA rise or clinical progression)." (PMID 16539730, 2006). "The mean relative CD24 expression value was 0.21 (range 0.013–1.02; median 0.14) in the Pca group and 0.08 (range 0.01–0.29; median 0.06) in the BPH group." (PMID 16539730, 2006). "Based on the RT-PCR protocol using LightCycler technology, the present study revealed a highly significant elevation of tissue CD24 mRNA expression in Pca patients compared to patients with a benign histology." (PMID 16539730, 2006). "Normalized CD24 transcript levels in 59 Pca cases were increased 2.69-fold on the average when compared to 55 BPH cases." (PMID 16539730, 2006). "This Pca patient population had a 2.69 times higher mean CD24 expression for Pca than for BPH." (PMID 16539730, 2006). "CD24 expression levels among Pca cases were not statistically associated with the tumor and lymph-node stage, the grading (WHO), the surgical margins, or the Gleason score." (PMID 16539730, 2006). "CD24 expression levels in Pca cases were not statistically associated with the tumor or lymph node stage or with grading (WHO), surgical margins, or the Gleason score." (PMID 16539730, 2006).
pertussis (1 paper, 2024). A contagious bacterial respiratory infection caused by Bordetella pertussis. "Other immune cells associated with increased pertussis risk include IgD+ CD38br AC and CD24+ CD27+ %B cells." (PMID 39612418, 2024).
plasma cell disorders (1 paper, 2022). "The fact that AL, like MM, is a plasma cell disorder treated by similar protocols may lead to a better understanding of the common mechanisms implemented by CD24 that affect the prognosis in AL." (PMID 35629039, 2022). "However, it is important to remember that MFC is not a mandatory part of the diagnosis of MM, and that MFC CD24 is not a part of the routinely used or recommended antigen panel used for diagnosis of MM and other plasma cell disorders." (PMID 35629039, 2022).
polyp (1 paper, 2023). A usually exophytic mass attached to the underlying tissue by a broad base or a thin stalk. "Similar plasma sEV subpopulation compositions were found in CPPs and CRCPs, and a statistically significant difference between polyp and cancer patients was found in the MFI of the CD9/CD24 sEV subpopulation." (PMID 37109070, 2023).
postmenopausal osteoporosis (1 paper, 2023). Metabolic disorder associated with fractures of the femoral neck, vertebrae, and distal forearm. "In line with serving as the osteoblast/adipocyte bipotent cell, the "bone to fat" tissue remodeling occurring in models of postmenopausal osteoporosis or after high fat diet exposure occur in part by reprogramming these CD24+CD29+SSCs to change their output of lineage-restricted precursors." (PMID 36747839, 2023).
proliferative glomerulonephritis (1 paper, 2023). A constellation of renal disorders characterized by an increase number of cells in the glomerulus; these disorders generally present with nephrotic syndrome, and generally progress to end stage renal failure over a matter of weeks to years, depending on the etiology. "The presence of hypertrophic CD24+ PECs, in a significantly greater number in lupus nephropathy biopsies than in controls, suggests that both proliferative glomerulonephritis and proteinuric milieu might induce an increment in these cells." (PMID 37594671, 2023).
retinopathy of prematurity (1 paper, 2016). A bilateral retinopathy characterized by neovascularization, scarring, retinal detachment, and eventually blindness. "One study showed that the loss of CD24 may have a deleterious effect on angiogenesis occurring in the second stage of retinopathy of prematurity (ROP) development." (PMID 27494878, 2016).
rhabdomyolysis (1 paper, 2013). Necrosis or disintegration of skeletal muscle often followed by myoglobinuria. "When isolated and injected intravenously into SCID mice with rhabdomyolysis-induced AKI, human CD133+CD24+CD106- cells engrafted into the nephrons, generating tubular cells." (PMID 23688352, 2013). "Further, CD24+CD133+ PECs contributed to damaged tubules and restored kidney function when injected into SCID mice with rhabdomyolysis-induced AKI." (PMID 23688352, 2013).
rhabdomyosarcoma (1 paper, 2022). A rare aggressive malignant mesenchymal neoplasm arising from skeletal muscle. "This study aimed to evaluate the expression of the selected stem cell markers CD24, CD44, CD133, and ALDH1A1 in rhabdomyosarcoma in children and to determine their prognostic significance in this disease." (PMID 36010245, 2022).
salivary gland mucoepidermoid carcinoma (1 paper, 2015). A carcinoma that arises from the salivary glands. "Together, these results suggest that ALDH1, CD44, CD10, and CD24 are highly expressed in salivary gland mucoepidermoid carcinoma when compared to normal salivary gland and that expression of ALDH1, CD10, and CD24 may be differentially regulated in more aggressive cell types." (PMID 26449187, 2015). "Collectively, these data indicate that the CD44/CD24 marker combination does not enable consistent identification of a unique population of highly tumorigenic cells in salivary gland mucoepidermoid carcinomas." (PMID 26449187, 2015).
schistosomiasis (1 paper, 2022). An infectious disease caused by parasitic trematodes of the genus Schistosoma that colonize human blood vessels and release eggs that can cause granulomatous reactions leading to acute (swimmer's itch or acute schistosomiasis syndrome) or chronic disease. "C108 has clear splenic cDC1 phenotype, high CD24 and XCR1, and relatively high CD86, and has clearly distinct group-wise effects: enriched after exposure to maternal schistosomiasis, but relatively reduced after exposure to treatment." (PMID 35833137, 2022).
serous papillary carcinoma (1 paper, 2006). "Weak to no signal was detected in a slide representing benign endometrioid adenomyofibroma when stained with CD24 antibody, while in contrast, serous papillary carcinoma exhibited moderate to strong CD24 staining in the nucleus and cytoplasm." (PMID 16969345, 2006).
severe combined immunodeficiency (1 paper, 2006). Severe combined immunodeficiency (SCID) comprises a group of rare monogenic primary immunodeficiency disorders characterized by a lack of functional peripheral T lymphocytes resulting in early-onset severe respiratory infections and failure to thrive. "Also, we did not observe metastasis of SUM1315 cells, with a 97% CD44+/CD24- subpopulation, in nude mice, although previous studies have shown bone metastasis of these cells in nonobese diabetic/severe combined immunodeficiency mice with humanized but not mouse bone." (PMID 17062128, 2006).
skin sarcoidosis (1 paper, 2024). Formation of non-necrotizing granulomas in the skin. "The results of recent independent studies of patients with skin sarcoidosis also revealed an increase in “naive” B-lymphocytes (CD20+CD27−IgD+) and “transitional” B-cells (CD24++CD38++) in peripheral blood." (PMID 39410592, 2024).
steatosis (1 paper, 2020). Increased lipid within the cytoplasm of cells. "Six progress-related genes (AKR1B10/SPP1/CD24/UBD/FABP4/STMN2) were found remarkably correlated with steatosis, ballooning, inflammation, fibrosis, and NAS in the progress of Normal/NAFL/NASH." (PMID 33574818, 2020).
T-cell leukemia (1 paper, 2008). A malignant disease of the T-lymphocytes in the bone marrow, thymus, and/or blood. "Leukemic cells from both groups of mice expressed variable levels of CD4, CD8, CD24, and CD25 cell surface markers, characteristic of bona fide TEL-JAK2 T-cell leukemia (data not shown)." (PMID 18596915, 2008).
teratoma (1 paper, 2025). A non-seminomatous germ cell tumor characterized by the presence of various tissues which correspond to the different germinal layers (endoderm, mesoderm, and ectoderm). "CD24 was highly expressed in adult YST, EC, and teratoma, aligning with its elevated levels in pediatric YST and EC, indicating a conserved immune escape mechanism through CD24 across age groups." (PMID 40621458, 2025).
Thrombocytopenia (1 paper, 2023). A reduction in the number of circulating thrombocytes. "However, given that acquired resistance and adverse events (e.g., acute anemia and thrombocytopenia) have been observed in systemic CD47/CD24 antibody administration, the feasibility of blocking CD47/CD24 alone or in combination in GBM remains uncertain." (PMID 37474548, 2023).
Thrombocytosis (1 paper, 2025). Increased numbers of platelets in the peripheral blood. "To further investigate the role of CD24 in thrombocytosis in MPN, we intercrossed Vav1-Cre;JAK2V617F mice with Cd24-/- mice to generate MPN mice on a CD24-deficient background." (PMID 40373279, 2025). "Similar results from CD24 KO or blockade exclude a prominent role of antibody-dependent cellular cytotoxicity and suggest thepareutic effects of CD24 inhibition in MPN thrombocytosis." (PMID 40373279, 2025).
tongue SCC (1 paper, 2026). "A study shows that MDSC activity and expansion being impeded by CD24 expression underlie the slow development of 4NQO-induced or orthotopically transplanted murine tongue SCC." (PMID 41585138, 2026).
trabecular carcinoma (1 paper, 2018). "Moreover, trabecular carcinoma and lesions with lymphocyte infiltration were also found in some tumors from the Cd24−/− mice." (PMID 29423273, 2018).
tubular adenoma (1 paper, 2022). A usually polypoid neoplasm arising from the glandular epithelium. "The expression rate of CD24 in normal mucosa, inflammatory polyp, tubular adenoma, villous adenoma, and adenocarcinoma of CRC increased gradually, and the expression rate of CD24 increased with the degree of differentiation of CRC." (PMID 35938128, 2022).
urolithiasis (1 paper, 2025). Stone(s) within the urinary tract. "Then, glycolithocholate levels partly positively mediated the associations between CD24 on transitional B cells and HLA DR on DC with urolithiasis, and the proportions were 9.64% and 8.84%, respectively." (PMID 40612664, 2025). "Our finding that B cell traits, Tregs panel, and one trait of CDC panel were linked with increased urolithiasis risk, including IgD-CD24-%lymphocyte, CD24 on transitional B cells, CD25 on IgD+ CD38-naïve, CD4 Treg% T cell, activated and resting Treg AC, and CD11c on myeloid DC." (PMID 40612664, 2025).
uveal melanoma (1 paper, 2024). A melanoma derived from melanocytes of the uveal tract. "A positive correlation was observed between CD24 expression levels and the infiltration of activated CD8+ T cells, activated CD4+ T cells, natural killer cells, activated dendritic cells, macrophages, monocytes, and neutrophils in SKCM, uveal melanoma (UVM), adrenocortical carcinoma (ACC), and UCS." (PMID 39791710, 2024).
vitamin D deficiency (1 paper, 2018). A nutritional condition produced by a deficiency of VITAMIN D in the diet, insufficient production of vitamin D in the skin, inadequate absorption of vitamin D from the diet, or abnormal conversion of vitamin D to its bioactive metabolites. "In vitamin D deficiency, only 60% go on to become the CD24- mature type, with equal rates of apoptosis between CD44+ and CD24- cells." (PMID 30046564, 2018).
yolk sac tumor (1 paper, 2025). A non-seminomatous malignant germ cell tumor composed of primitive germ cells. "In contrast, yolk sac tumors displayed an immunosuppressive environment with high CD24 and PVR expression, indicative of unique immune evasion mechanisms." (PMID 40621458, 2025).
tumor (1,135 papers, 2003 to 2026). "The association between CD24 and tumor aggressiveness is ascertained by in vitro functional approaches." (PMID 41585138, 2026). "Beyond its associations with tumor aggressiveness and stem-like phenotypes, CD24 functions at a critical interface between tumor-intrinsic plasticity and myeloid-driven immune suppression within the tumor microenvironment (TME)." (PMID 41972163, 2026). "The decreased CD24 mRNA expression induced by Doxy treatment in tumor grafts was also associated with the decreased SEC14L2 expression." (PMID 41585138, 2026). "The association is found between the inducible CD24 shutdown and the slower syngeneic orthotopic tumor growth, which further substantiates the linkage of CD24 to tumor progression." (PMID 41585138, 2026). "Due to the high expression of CD24 in tumor cells and its close association with mechanisms of resistance to radiochemotherapy, targeting CD24 can precisely deliver cancer cell killing and suppress the emergence of chemoradiotherapy resistance." (PMID 40486886, 2025). "Among the tested markers, CD24 positivity in ≥30% of the tumor cells was significantly associated with disease-free survival (DFS), metastasis-free survival (MFS), and overall survival (OS)." (PMID 40647395, 2025). "For instance, in ovarian and breast cancers, CD24 engages with Siglec-10 found on tumor-associated macrophages, thereby promoting immune evasion." (PMID 40830893, 2025). "MSLN also upregulates CD24 expression via the activation of the Wnt/β-catenin pathway, which induces pro-tumor M2 polarization of tumor-associated macrophages." (PMID 41400642, 2025). "CD24, a cell surface glycoprotein, was linked to tumor progression, metastasis, and cancer stem cell properties." (PMID 40821783, 2025). "In this study, we identified a tumor subgroup characterized by high CD24 and MUCL1 expression, which was linked to poor prognosis and invasive behavior." (PMID 41142825, 2025). "High expression of CD24 is associated with short survival and both anti-CD24 on tumor cells and anti-Siglec-10 on tumor-associated macrophages effectively promote tumor cell phagocytosis by macrophages." (PMID 40835598, 2025). "High expression of CD24 is also slightly associated with larger tumor size, indicating resistance to radiotherapy." (PMID 40486886, 2025). "CD24 promotes tumor migration and inhibits anti-tumor responses associated with immune checkpoint therapy." (PMID 40510161, 2025). "Due to its diverse post-translational modifications, CD24 is associated with tumor development, invasion, and metastasis." (PMID 40486886, 2025). "In high-grade serous ovarian carcinoma, tumor-associated mesothelin activates Wnt/β-catenin signaling, subsequently upregulating CD24 expression." (PMID 41417432, 2025). "One study mentioned expression in the entire tumor area, and concluded that CD24 expression was associated with worse survival." (PMID 39904885, 2025). "A high CD44/CD24 ratio, particularly the CD44 high/CD24 low phenotype, is characteristically associated with a higher proportion of CSCs within a tumor." (PMID 40227834, 2025). "CD24 is also considered a marker of cancer stem cells, with its expression level being closely associated with tumor invasion, metastasis, and prognosis." (PMID 41195275, 2025). "A univariate analysis indicated that tumor histology (p = 0.041) and CD24 expression level (p = 0.021) were risk factors for OS." (PMID 41354057, 2025). "For instance, it can promote the polarization of M2-type tumor-associated macrophages by activating the CD24-Siglec-10 signaling axis; moreover, its high expression levels are negatively correlated with reduced CD8+ T cell infiltration." (PMID 41400642, 2025). "First, we explored the effects of CD24a ablation on the infiltration of tumor-associated macrophages (TAMs), given that CD24 is known to suppress macrophage phagocytic function." (PMID 40783744, 2025).